OCLN (occludin)
Diseases named in the same sentence as OCLN in open-access papers (continued):
Sharing a sentence is not in itself a finding about the gene and the disease.
diabetes (continued). "In line with our results, Ricci and co-workers showed the abnormal histology, seminiferous epithelium cytoarchitecture, occludin distribution pattern, hypertrophy, and abnormally distribution of Leydig cells in the testicular tissue of the streptozotocin-induced diabetes rats." (PMID 36144807, 2022). "Our result of restoration of OCLN mRNA expression in psoriasin supplemented high glucose treated uroepithelial cells further confirmed the vital role of psoriasin in maintenance of epithelial integrity in diabetes." (PMID 36127330, 2022). "In line with this hypothesis, urine exfoliated cells from patients with diabetes, demonstrating lower levels of psoriasin, presented a clear downregulation of OCLN." (PMID 36127330, 2022). "However, CTRP3 preserves iBRB function in NPDR by preventing diabetes-suppressed Occludin and Claudin-5 (tight junction protein) expression in an AMPK-dependent manner." (PMID 35269401, 2022). "In addition, diabetes downregulated tight junction proteins (ZO-1, occludin, and claudin-1) and increased intestinal permeability to impair the intestinal barrier." (PMID 34084135, 2021). "As expected, retinas of Akita mice 12 weeks after the onset of diabetes showed increased number of leukocytes adhered to blood vessels, downregulated expression of the tight junction proteins occludin and ZO-1, and enhanced dextran leakage from vessels, compared with respect to those of WT mice." (PMID 34750361, 2021). "However, TWOD and CaD treatment significantly attenuated the alterations in occludin and claudin-5 expressions induced by diabetes." (PMID 28367226, 2017). "However, oral administration of AKE for 16 weeks blocked diabetes-induced blood–retinal barrier (BRB) breakdown and the loss of occludin, which is an important tight junction protein." (PMID 29169356, 2017). "Thus, diabetes damaged the TJ protein, and occludin and claudin-5 injuries accelerated the development of diabetes." (PMID 28367226, 2017). "Diabetes-induced occludin degradation was attenuated by the treatment of KIOM-79." (PMID 22916281, 2012). "Ten days after diabetes induction, retinal occludin content in eyes that received rAAV-lacZ was 11.35±3.57 pixels and 34.73±3.17 pixels in eyes that received rAAV-angiostatin occludin, a statistically significant reduction (n=5, p=0.041)." (PMID 17293777, 2007). "The barrier protein occludin is decreased in experimental diabetes." (PMID 17293777, 2007). "Our present results showed decreased levels or decreased tendency of ZO-1, occludin, and claudin-1 in the DM group, indicative of disruption of the tight junction barrier under diabetes." (PMID 34692563, 2021). "Diabetes induction in the floxed control mice decreased levels of the RPE tight junction protein ZO-1 and adherens junction proteins occludin and E-cadherin; these decreases were rescued in Akt2 cKO diabetic mice." (PMID 37443129, 2023). "ZO-1 and occludin expressions were significantly reduced in rats with HFD- and STZ-induced diabetes when compared with the control group (p = 0.0077 and p = 0.0189, respectively), suggesting an impaired tight-junction function of BBB in the model group." (PMID 35899118, 2022). "Impaired morphology of the colon tight junction and reduced ZO-1 and occludin expressions were observed in the rats with HFD- and STZ-induced diabetes." (PMID 35899118, 2022). "In the current study, we report that AMPK activation in the retina was inhibited in diabetes-induced NPDR, consequently suppressing the crucial molecules Occludin and Claudin-5 in iBRB." (PMID 35269401, 2022). "Diabetes was also reported to impair the permeability of BBB by down-regulating occludin and ZO-1 in STZ-induced diabetes model." (PMID 28794417, 2017). "To determine the mechanism of RRP effect in diabetes-induced vascular leakage, we examined the protein expression of VEGF and occludin (important tight junction protein)." (PMID 23662142, 2013).
diabetes (continued). "Several chronic disease models show decreases in total spinal occludin protein such as EAE, diabetes, and nerve injury." (PMID 22713725, 2012). "Occludin was significantly increased in all protein lysate samples from the retinal vasculature of anti-STEAP4 treated diabetic mice than untreated diabetic mice (n = 5/group); 2-months post-diabetes." (PMID 40002391, 2025). "cPWWP2A directly regulates pericytes biology but indirectly regulates ECs biology via EVs carrying cPWWP2A, which inhibited miR-579 activity, increased expression of angiopoietin 1/occludin/SIRT1, and ultimately alleviates diabetes-induced retinal vascular dysfunction." (PMID 36686474, 2022). "Among PWH, in multivariable models, the relationship between Faith’s PD and occludin levels remained significant and was not influenced by including hyperlipidemia or diabetes mellitus or their interactions as covariates." (PMID 34696320, 2021). "This study supports this finding by showing that serum occludin levels in the diabetes group were slightly higher than the non-diabetic group." (PMID 33269096, 2020). "Additionally, univariate logistic regression analysis indicated a negative correlation between plasma Occludin levels in the Type 2 Diabetes Mellitus (T2DM) group and APN." (PMID 39354565, 2024). "Diabetes decreases the amount of occludin and claudin-5, but not the content of ZO-1." (PMID 26389948, 2015).
Cerebral ischemia (45 papers, 2010 to 2025). Restriction of arterial blood supply to the brain associated with insufficient oxygenation to support the metabolic requirements of the tissue. "In a rat model of cerebral ischemia, accumulation of zinc in ischemic microvessels was observed, leading to the loss of tight junction proteins (occludin and claudin-5)." (PMID 37840921, 2023). "In a rat model, cerebral ischemia induced an increase of blood occludin with a loss of occludin from ischemic cerebral microvessels and BBB damage." (PMID 32600371, 2020). "In the present study, we evaluated how EA at GV20 and ST36 changed infarct volumes, neurological deficits, and expression levels of TJ-associated proteins ZO-1, claudin-5, and occludin following cerebral ischemia reperfusion within 7 d in Sprague-Dawley rats." (PMID 25009574, 2014). "It is relevant to note that in the studies of the blood–brain barrier, it has been shown that UTI protected the brain against cerebral ischemia/reperfusion injury through reversing the loss of ZO-1 and occludin in the brain endothelia in mice with middle cerebral artery occlusion." (PMID 30150933, 2018). "In animal models of permanent brain ischemia and ischemia-reperfusion injury, the loss of occludin in the blood-brain or blood-retinal barriers is also associated with itch activation and itch-mediated occludin ubiquitination." (PMID 29080116, 2018). "Our previous animal studies showed that occludin in microvessels was degraded during cerebral ischemia, with fragments of occludin entering the blood circulation." (PMID 37721332, 2024). "Cerebral ischemia similarly decreases the expression levels of TJ proteins such as occludin, ZO-1, Claudin-5, and JAM-A." (PMID 36806348, 2023). "The MCAO in vivo model also showed that cerebral ischemia rapidly induced the degradation of occludin and redistribution of claudin-5 in ischemic cerebral microvasculature." (PMID 35627746, 2022). "In the process of cerebral ischemia and reperfusion, the expression of occludin along the blood vessel changes from a continuous state to an intermittent state or even disappears, and its decrease has been used to determine the degree of BBB injury." (PMID 35685645, 2022). "Several recent studies have found that MMP-9 is involved in the expressions of E-cadherin or occludin in cerebral ischemia–reperfusion injury, acute lung injury, and acute kidney injury." (PMID 34425812, 2021). "Cerebral ischemia induces a rapid degradation of claudin and occludin, which disrupts the TJ structure and renders the endothelial cells more vulnerable, accelerating their damage." (PMID 34795584, 2021). "Cerebral ischemia led to lower levels of structural components of the BBB such as tight junction proteins (occludin, claudin-1 and ZO-1) in the MCAO/R group compared with the sham group (P < 0.001)." (PMID 34857032, 2021). "Following induction of reversible cerebral ischemia in the rat, capillaries were isolated, and enhanced tyrosine phosphorylation of endothelial occludin was demonstrated, which was associated with BBB disruption following cerebral ischemia." (PMID 32457645, 2020). "Following the onset of cerebral ischemia, occludin protein is cleaved from the cerebral microvessels, some of which are released into the blood circulation, leading to increased serum occludin levels." (PMID 33269096, 2020). "Several studies have reported that the alteration or decrease in occludin during cerebral ischemia results in increased BBB permeability." (PMID 32169114, 2020). "Taken together, our data from both in vitro and in vivo models demonstrate that autophagy is an important pathway responsible for occludin degradation during cerebral ischemia." (PMID 32169114, 2020). "Animal studies have demonstrated that high levels of occludin remain for more than 24 h after acute brain ischemia and are stable in comparison to the parameters taken at 12 h." (PMID 33182224, 2020).
Cerebral ischemia (continued). "The results of animal studies revealed that 4 h after brain ischemia onset, the concentration of occludin rapidly increases." (PMID 33182224, 2020). "Some authors have demonstrated that high levels of occludin remain for more than 24 h after acute brain ischemia and are stable in comparison to the parameters taken at 12 h." (PMID 33182224, 2020). "In an opposite approach, normobaric hyperoxia protected the BBB, and the expression and distribution of occludin against MMP-9–mediated effects in cerebral ischemia." (PMID 31684130, 2019). "In a multifocal cerebral ischemia model, Src kinase dependent tyrosine phosphorylation of occludin was found to contribute to barrier disruption." (PMID 31684130, 2019). "To evaluate intestinal barrier integrity in the first days after brain injury, we examined claudin-1 and occludin expression in the membrane fraction from ileum and colon homogenates 1 and 3 days after cerebral ischemia." (PMID 30510535, 2018). "Immunofluorescence staining revealed the increased levels of ZO-1 and occludin even following cerebral ischemia, suggesting that Shuanghe-tang reduces BBB disruption via increases in the level of tight junction proteins." (PMID 29599893, 2018). "Here, we investigated the temporal evolution of BBB damage within the first 4.5 hours of cerebral ischemia and its correlation with the change of blood occludin levels." (PMID 28079139, 2017). "We show that EA promotes BBB tightness by alleviating the disruption of the TJ-related proteins ZO-1, claudin-5, and occludin during the process of cerebral ischemia reperfusion." (PMID 25009574, 2014). "Increased phosphorylation of occludin at tyrosine residue is shown in a focal cerebral ischemia model of the BBB disruption, further supporting a role for tight junction protein phosphorylation in regulating the permeability of blood vessels." (PMID 21078165, 2010). "All our results suggested that BMSC-sEVs could regulate Cav-1-mediated autophagic degradation of ZO-1 and Occludin after cerebral ischemia." (PMID 39781452, 2025). "In addition, in a rat model of cerebral ischemia, Occludin expression in the blood–brain barrier was observed to initially increase at 24 h and subsequently decrease by 72 h." (PMID 39354565, 2024). "Overexpression of SIRT1 in BMECs rescued claudin-5, occludin, ZO-1, and VE-cadherin expression, while stabilizing claudin-5/ZO-1 interactions to protect against senescence-induced brain endothelial barrier hyperpermeability, cerebral ischemia, and OGD/R." (PMID 39598406, 2024). "Furthermore, although expression of the tight junction proteins (TJs) zonula occludens 1 (ZO-1) and occludin was significantly reduced after cerebral ischemia/reperfusion, these effects were attenuated by NBP treatment." (PMID 36909178, 2023). "MMP-2 mediated occludin degradation leads to BBB disruption during cerebral ischemia." (PMID 37962463, 2023). "Our recent animal study showed that the level of blood occludin fragments was correlated with BBB permeability after cerebral ischemia and may serve as a potential biomarker for BBB damage." (PMID 34512266, 2021). "Two major occludin fragments were identified in the blood during cerebral ischemia." (PMID 28079139, 2017). "EA pretreatment for five days was recently shown to significantly reduce BBB permeability and brain edema, which were correlated with alleviation of the degradation of tight junction proteins occludin and claudin-5 following cerebral ischemia-reperfusion in rats." (PMID 26952102, 2016). "Single-dose of minocycline treatment immediately after reperfusion onset effectively reduces brain injury in rats subjected to transient focal cerebral ischemia due to inhibition on MMP-2/9-mediated occludin degradation and attenuation of caspase dependent and independent apoptotic pathways." (PMID 26925194, 2016).
Cerebral ischemia (continued). "Our data suggested that during cerebral ischemia, activation of TRPV4 may increase the activated MMP-9 level, leading to the loss of ZO-1 and occludin." (PMID 25914628, 2015). "Therefore, understanding of the mechanism by which the integrity of TJs is maintained and the ZO-1, occludin, claudin-5 expression is regulated has potential implication for the treatment of cerebral ischemia." (PMID 23894369, 2013). "Based on occludin protein as a potential biomarker for cerebral ischemia‐induced BBB injury and BBB disruption after ICH onset being engaged in PHE development, we further focused on ICH patients to determine whether the baseline level of occludin was associated with the severity of the PHE." (PMID 37721332, 2024). "Together with our early reports, the present data indicate that during cerebral ischemia, blockage of TRPV4 may inhibit the activation of MMP-9 and the loss of ZO-1 and occludin, which helps to reduce the disruption of BBB integrity and the subsequent vasogenic brain edema and brain injury." (PMID 25914628, 2015). "Furthermore, a recent study showed that Ang-1 may decrease the permeability of BBB in brain ischemia by up-regulating the expression of ZO-1 and occludin." (PMID 23894369, 2013). "Unlike occludin Ser/Thr phosphorylation associated with barrier formation occludin Tyr-phosphorylation was reported to be associated with increased permeability of cultured rat brain endothelial cells exposed to glutamate, as a way to mimic cerebral ischemia." (PMID 23140302, 2012). "Aging, cerebral ischemia, and OGD/R have been shown to reduce the expression of SIRT1, occludin, claudin-5, VE-cadherin, and ZO-1 in BMECs, leading to dysregulated BBB permeability." (PMID 39598406, 2024). "The expression of tight junction proteins ZO-1 and occludin, matrix metalloproteinase MMP-2, and MMP-9 in cerebral cortex tissue of cerebral ischemia/reperfusion rats at 24 h were quantitatively detected by the Western blot technique." (PMID 38927572, 2024). "We observed decreased expression of occludin and ZO1 after cerebral ischemia, consistent with previous studies." (PMID 35685645, 2022). "Our recent experimental study in rats showed that occludin, one of the tight junction proteins in BBB, can be cleaved into fragments after cerebral ischemia and then released into blood circulation." (PMID 34512266, 2021). "Previous animal experiments have reported that cerebral ischemia results in the activation of MMP-2 and MMP-9 in brain tissue, leading to the degradation of occludin and destruction of the BBB." (PMID 32884584, 2020). "The administration of 4-amino-5-(4-chlorophenyl)-7-(t-butyl) pyrazolo [3,4-d]pyrimidine (PP2), a Src-family tyrosine kinase inhibitor, diminished the phosphorylation of occludin, and reduced the BBB disruption following cerebral ischemia." (PMID 32457645, 2020). "For example, blocking MMP activation or MMP-9 knock-out (KO) prevented degradation of CLN-5 and OCLN, and attenuated BBB disruption, in cerebral ischemia/reperfusion animal models." (PMID 30699952, 2019). "In the wild type mice, cerebral ischemia and reperfusion led to remarkable Evans blue extravasation, significantly increased gp91phox and MMP-9 levels and decreased occludin levels in the ischemic brain tissue." (PMID 22146586, 2011). "Additionally, minocycline was shown to enhance the levels of TJs proteins, specifically ZO-1, occludin, and claudin-5, and to decrease the BBB permeability in an in vivo cerebral ischemia rat model, a condition that also compromises BBB function." (PMID 36009536, 2022). "However, a single dose of LGU (0.24, 2.16 mg/kg) in the tail vein can up-regulate the expression of tight junction proteins ZO-1 and occludin and inhibit the expression of MMP-9 after cerebral ischemia/reperfusion, suggesting that LGU may up-regulate tight junction proteins ZO-1 and occludin." (PMID 38927572, 2024).
Cerebral ischemia (continued). "More importantly, for patients with non-reperfusion therapy, if the blood vessels are not recanalized, cerebral ischemia and the continued hypoxia may result in serious BBB damage and irreversible change, which corresponds to significant increases of serum occludin." (PMID 33269096, 2020).